RASSF10-DT (RASSF10 divergent transcript)
Synonyms: formerly LINC02738
Gene: Long non-coding RNA gene on chromosome 11 (12,980,022 to 13,009,159, reverse strand). Ensembl gene ENSG00000254670.
Diseases named in the same sentence as RASSF10-DT in open-access papers:
RASSF10-DT is named in the same sentence as 1 disease in open-access papers, as found by Europe PMC text mining. Sharing a sentence is not in itself a finding about the gene and the disease.
RASSF10-DT shares sentences with these, for which no sentence is quoted: renal carcinoma (1 paper).